CD40 (CD40 molecule)
Diseases named in the same sentence as CD40 in open-access papers (continued):
Sharing a sentence is not in itself a finding about the gene and the disease.
cervical carcinoma (13 papers, 2011 to 2024). A carcinoma arising from either the exocervical squamous epithelium or the endocervical glandular epithelium. "The CD40 ligation have a direct influence in the susceptibility of cervical carcinoma cells to cytotoxic T lymphocyte (CTL)-mediated killing." (PMID 37970926, 2023). "Functional studies in the future are necessary to elucidate how polymorphisms regulate CD40 expression, especially their role in cervical cancer pathogenesis." (PMID 37691121, 2023). "In fact, quercetin, among other compounds, increases the susceptibility of cervical carcinoma cells to CD40L-induced apoptosis reversing CD40-mediated dissociation of the translational repressor eIF4E-binding protein from the initiation factor eIF4E." (PMID 21750559, 2011). "A recent study showed that high expression of CD40/CD40L is associated with a better prognosis in patients with cervical cancer, but whether CD40 activation affects the radiosensitivity of cervical cancer cells is unclear." (PMID 39696986, 2024). "With further study of the CD40 gene, it may be a useful biomarker for evaluating the risk of developing cervical cancer and may also be used as a target for therapy." (PMID 37691121, 2023). "Previous studies on CD40 gene polymorphisms and cervical cancer have been very limited." (PMID 37691121, 2023). "In this study, we find that CD40 ligation promotes autophagosome formation and consequently promotes autophagic flux in cervical cancer cells." (PMID 39696986, 2024). "In summary, our study demonstrated that CD40 activation is associated with ATG13 expression and autophagy by increasing the phosphorylation level of ERK in cervical carcinoma cells." (PMID 39696986, 2024). "In the present study, activating CD40 signaling enhanced autophagic flux and promoted the radiosensitivity of cervical cancer cells, which was reversed by an autophagy inhibitor." (PMID 39696986, 2024). "Taken together, these results suggest that CD40 activation facilitates autophagy in cervical carcinoma cells." (PMID 39696986, 2024). "In this study, we used cervical carcinoma cells and demonstrated that CD40 ligation enhanced the formation of autophagosomes, consequently promoting autophagic flux by increasing ATG13 expression." (PMID 39696986, 2024). "Taken together, our results provide new evidence for the involvement of the CD40 pathway in autophagy and radiotherapy in cervical cancer cells." (PMID 39696986, 2024). "To better understand the relationship between CD40 and cervical cancer, we evaluated CD40 expression in cervical cancer cell lines at the RNA and protein levels." (PMID 37970926, 2023). "Higher CD40 expression was observed in cervical cancer cell lines derived from squamous cell carcinomas than from adenocarcinomas." (PMID 37970926, 2023). "Search of CD40/CD40L expression in cervical cancer tissues in public data sets revealed that about 83% of squamous cell carcinomas express CD40 compared to other cervical tumor subtypes." (PMID 37970926, 2023). "A significantly higher CD40 expression was observed in cervical cancers of the squamous cell subtype than adenocarcinomas or other histological tumor types." (PMID 37970926, 2023). "In this study, we aimed to examine CD40 expression in different cervical cancer cell lines at both RNA and protein levels and analyzed CD40 expression and its prognostic role in cervical cancer patients." (PMID 37970926, 2023). "Recent data pointed out that CD40 presents good discriminatory properties for cervical cancer, where secreted CD40 exhibits high sensitivity and specificity, making this protein an interesting target for immunotherapy combined with radiation." (PMID 37970926, 2023). "In summary, CD40 was expressed in cervical cancer cell lines derived from squamous cell carcinomas, especially SiHa and SW756." (PMID 37970926, 2023).
cervical carcinoma (continued). "We investigate the in-situ administration of the anti-CD40 given well-known systemic toxicity limitations, and the minimal invasiveness of such a treatment approach for cervical cancer." (PMID 32331490, 2020). "Here, we attempt to improve current therapy toward cervical cancer, especially its recurrence, according to using CD40-based HPV16 E7 vaccine which solves problems existing in peptide vaccines." (PMID 32536922, 2020). "Secondly, we identify CD40, CD27, and TIM-3 to specifically discriminate cervical cancer from other groups and CD40, CD28, and TLR2 to positively correlate to genital inflammation." (PMID 32802959, 2020). "Regarding CD40 expression in cervical cancer tissues, some reports indicate that CD40 signal becomes stronger in cancer compared to low-grade or normal epithelium." (PMID 30562965, 2018). "Moreover, the CD40 signaling pathway enhances the radiosensitivity of cervical cancer cells by increasing autophagy level." (PMID 39696986, 2024). "However, the role and mechanism of CD40 in the autophagy and radiosensitivity of cervical cancer cells are still unclear." (PMID 39696986, 2024). "To evaluate whether CD40 ligation induces autophagy in cervical cancer cells, we first analyzed the expression of endogenous LC3B-II, a marker of autophagosomes, and the level of p62, an autophagy cargo receptor, in HeLa/CD40 cells by western blot analysis." (PMID 39696986, 2024). "Importantly, we demonstrated that CD40 ligation-induced autophagy increases the radiosensitivity of cervical cancer cells." (PMID 39696986, 2024). "Furthermore, we demonstrate that CD40 ligation-induced autophagy increases the radiosensitivity of cervical cancer cells." (PMID 39696986, 2024). "We demonstrated that CD40 activation can increase the level of autophagy in cervical cancer cells." (PMID 39696986, 2024). "This is in agreement with the high levels of CD40 protein expression in cervical cancer tissues." (PMID 37970926, 2023). "Altogether, these data indicated that CD40 can serve as a therapeutic target for cervical cancer." (PMID 37970926, 2023). "Studies conducted in vivo and in vitro found that, in contrast to healthy cervical epithelium and non-cancerous keratinocyte cell lines transfected with HPV-DNA, oncogenic HPV positive cervical cancer and HPV-positive cervical cancer cell lines expressed CD40 at high levels." (PMID 37691121, 2023). "Therefore, the role of CD40 and other genes in the occurrence and development of cervical cancer remains to be further studied." (PMID 37691121, 2023). "Based on the review conducted by Moerman-Herzog and Nakagawa, we gathered important information about CD40 ligation on normal keratinocytes or on cervical cancer cells, showing that this ligation amplifies inflammatory reactions due to chemokine secretion to recruit leukocytes." (PMID 37970926, 2023). "Here, we report results in animal models of advanced cervical cancer, showing that anti-CD40 therapy can effectively boost the abscopal effect, whereby radiotherapy of a tumor at one site can engender therapeutically significant responses in tumors at distant untreated sites." (PMID 32331490, 2020). "As a first step to investigate this hypothesis, this study investigates whether one fraction of radiotherapy combined with anti-CD40 can boost the abscopal effect in mouse models of advanced cervical cancer." (PMID 32331490, 2020). "This justifies a hypothesis that rational use of radiotherapy with the immunoadjuvant anti-CD40 can significantly boost the abscopal response or cure rates for advanced cervical cancer." (PMID 32331490, 2020). "However, there were few reports on the relationship between the CD40 gene and cervical cancer." (PMID 37691121, 2023). "However, CD40 was significantly higher in cervical carcinoma than in normal cervix, maybe involved in neovascularization or enhanced by a cytotoxic immune response." (PMID 30562965, 2018).
cervical carcinoma (continued). "In this study, we investigated CD40/CD40L transcriptional and protein levels in cervical cancer cell lines and tumors." (PMID 37970926, 2023). "We observed that SiHa (HPV16) and SW756 (HPV18) cell lines presented higher transcriptional levels of CD40 expression than normal keratinocytes (PHK) and HPV-negative cervical cancer cell line, C33A." (PMID 37970926, 2023). "In addition, CD40 may be involved in neovascularization of cervical carcinoma, suggesting that CD40 could act as a biomarker together with VEGF to evaluate the risk of cervical cancer development or be used as a target for therapy." (PMID 37970926, 2023). "High specificity and sensitivity of secreted CD40, CD27, and TIM-3 for cervical cancer make these proteins potential therapeutic targets for immunotherapy with radiation." (PMID 32802959, 2020). "Previous reports also demonstrated that CD40, PD-1, and TIM-3 are overexpressed in cervical carcinoma tissues compared with normal cervix, which is consistent with our CVL findings." (PMID 32802959, 2020). "Elevated levels of CD40, HVEM, PD-1, and TIM-3 connected cervical carcinoma to genital inflammation, whereas LAG-3 connected carcinoma to dysbiotic microbiota and TLR2 bridged genital inflammation and Lactobacillus dominance." (PMID 32802959, 2020). "Biomarker discovery analysis revealed that three immune checkpoint molecules, specifically CD40, CD27, and TIM-3, exhibit excellent or good discriminatory properties for cervical carcinoma compared to healthy controls and dysplasia." (PMID 32802959, 2020). "Third, cervical cancer is a complex disease affected by multiple genes, but we only studied the limited sites of the CD40 gene, and other functional genes and SNPs have not been explored." (PMID 37691121, 2023). "Cervical carcinoma cells have been shown to present a lower CCL2 secretion in response to CD40 ligation compared to non-tumorigenic HPV-positive cells." (PMID 37970926, 2023). "Furthermore, we analyzed CD40 and CD40L expression in cervical cancer tissues and their prognostic value based on public databases." (PMID 37970926, 2023). "Combination therapies with monoclonal antibodies targeting CD40, CD27, or TIM-3 might be a potential approach to achieve better therapeutic outcomes in advanced and recurrent cervical cancer." (PMID 32802959, 2020). "Kaplan-Meier survival estimates, based on dichotomized protein expression data, subsequently confirmed that patients with cervical cancer with high CD40 and high CD62LCD45RACD95CD122 protein expression had significantly longer OS (CD40, p < 0.05; CD62LCD45RACD95CD122, p < 0.05)." (PMID 32536922, 2020). "Nevertheless, other studies indicate that not all cervical cancer cases display CD40 signal or even, most of the cancer cases analyzed exhibit a weak signal for CD40 staining." (PMID 30562965, 2018).
diabetic retinopathy (13 papers, 2009 to 2026). "Another study reported upregulation of CD40, TRAF2, and TRAF6 in patients with diabetic retinopathy, where CD40 was associated with the expression of pro-inflammatory molecules such as intercellular adhesion molecule 1 (CD54), CCL2, and TNFα." (PMID 38554187, 2024). "Endothelial cells from patients with diabetic retinopathy exhibited increased CD40 expression that was associated with increased CML staining in these cells or the presence of CML surrounding endothelial cells." (PMID 38474393, 2024). "Together, increased staining with the anti-CML antibody in extracellular matrix proteins in patients with diabetic retinopathy was associated with increased CD40 expression in endothelial and Müller cells." (PMID 38474393, 2024). "Deletion of CD40 in diabetic mice decreased inflammatory responses linked to the pathogenesis of diabetic retinopathy, such as retinal leukostasis, capillary degeneration, ICAM-1 upregulation and protein nitration." (PMID 37958563, 2023). "Our findings suggest an interconnection between CD40 and AGEs that may help explain why targeting a single pathogenic pathway effectively controls diabetic retinopathy." (PMID 38474393, 2024). "Immunohistochemistry studies revealed areas of increased staining with the anti-CML antibody in extracellular matrix proteins in the retinas of patients with diabetic retinopathy, and these areas were associated with increased CD40 expression in retinal endothelial and Müller cells." (PMID 38474393, 2024). "We hypothesized that the CD40-TNF Receptor Associated Factor 6 (TRAF6) axis plays a pivotal role in the onset of diabetic retinopathy, and that the CD40-TRAF6 axis would be a prime therapeutic target for early-stage non-proliferative diabetic retinopathy." (PMID 36309487, 2022). "Moreover, we report that areas of increased staining with an anti-CML antibody in the extracellular matrix proteins, fibronectin and laminin, are associated with increased expression of CD40 in endothelial and Müller cells in the retinas of patients with diabetic retinopathy." (PMID 38474393, 2024). "Here we review the role of CD40 as an upstream inducer of these abnormalities and the development of diabetic retinopathy." (PMID 42123447, 2026). "As CD40-driven ICAM-1 expression and CCL2 production are essential for the pathogenesis of inflammatory diseases, including diabetic retinopathy, advanced glycation end products-mediated CD40 dysregulation is functionally relevant." (PMID 40005847, 2025). "CD40 expression is elevated in endothelial cells and retinal Müller cells from mice and humans with diabetic retinopathy." (PMID 38474393, 2024). "In summary, we report that CD40 and AGEs, two important drivers of diabetic retinopathy, are interrelated at the level of retinal cells in the diabetic retina." (PMID 38474393, 2024). "Taken together, these findings support that CD40 upregulation is an important event in the pathogenesis of diabetic retinopathy." (PMID 38474393, 2024). "Despite the various factors that promote the development of diabetic retinopathy, genetic disruption of CD40 is sufficient to prevent the development of this disease, and pharmacologic inhibition of CD40 signaling ablates inflammation in the diabetic retina." (PMID 38474393, 2024). "The expression of CD40 is elevated in endothelial and Müller cells in the retinas from patients with diabetic retinopathy." (PMID 38474393, 2024). "CD40 expressed in Müller cells plays a central role in the induction of inflammatory responses and the development of diabetic retinopathy." (PMID 38474393, 2024). "To assess the in vivo relevance of AGEs in CD40 upregulation, we examined AGE-induced protein modification and CD40 expression in posterior poles from patients with diabetic retinopathy." (PMID 38474393, 2024).
diabetic retinopathy (continued). "Our studies suggest that AGEs promote CD40 upregulation, which raises the possibility that CD40 and AGEs work together to induce events critical for the development of diabetic retinopathy." (PMID 38474393, 2024). "CD40 induces pro-inflammatory responses in endothelial and Müller cells and is required for the development of diabetic retinopathy (DR)." (PMID 38474393, 2024). "Studies in mice uncovered that CD40 induces inflammation in the diabetic retina and is required for the early development of diabetic retinopathy." (PMID 35920844, 2022). "Through ATP release, CD40 signalling in retinal Müller cells triggers in myeloid cells P2X7-dependent expression of proinflammatory molecules involved in the pathogenesis of diabetic retinopathy." (PMID 35920844, 2022). "Altogether, replacing WT CD40 with CD40 ΔT2,3 in Müller cells is sufficient to disrupt vascular inflammatory responses in the diabetic retina and the development of experimental diabetic retinopathy." (PMID 35920844, 2022). "This work identified CD40 in Müller glia as a central regulator of inflammation and development of early diabetic retinopathy." (PMID 31921199, 2019). "Immunological mechanism studies show that the up-regulation of ICAM1 and other inflammatory factors in the retina of diabetic retinopathy patients may be related to the pathway mediated by CD40 and its ligands." (PMID 39199149, 2024). "Moreover, the expression of CD40 in Müller cells is increased in mice and patients with diabetic retinopathy." (PMID 38474393, 2024). "Importantly, replacing WT CD40 by CD40 ΔT2,3 was sufficient to prevent the development of diabetic retinopathy." (PMID 35920844, 2022). "The importance of CD40 has been examined in animal models of diabetic retinopathy." (PMID 35920844, 2022). "CD40 expressed in Müller cells is a central driver of diabetic retinopathy." (PMID 35920844, 2022). "The role of CD40 as regulator of inflammation and development of diabetic retinopathy indicates that CD40 may represent a therapeutic target against this disease." (PMID 35920844, 2022). "We hypothesise that disruption of the CD40-driven molecular events that trigger this cascade prevents/treats diabetic retinopathy in mice." (PMID 35920844, 2022). "This approach could be effective against diabetic retinopathy and numerous inflammatory disorders driven by CD40." (PMID 35920844, 2022). "CD40 expressed in Müller cells is pivotal for the development of diabetic retinopathy." (PMID 35920844, 2022). "Importantly, CD40−/− mice are protected from I/R-induced retinopathy and early diabetic retinopathy." (PMID 31921199, 2019). "Some processes relevant to diabetic retinopathy were found upregulated in diabetic aqueous samples including CD40, C reactive protein, erythropoietin, fatty acid binding protein, FGF basic, fibrinogen, IL-1ra, IL-8, leptin, macrophage-derived chemokine (MDC), MMP-2, and VEGF." (PMID 19145248, 2009). "Interestingly, a recent investigation performed in CD40 knock-out mice showed that these animals exhibited diminished inflammatory responses and they were protected from the development of diabetic retinopathy, suggesting that CD40 promotes the development of early diabetic retinopathy." (PMID 25723058, 2014). "Interestingly, CD40 promotes ICAM-1 upregulation, leukostasis, and retinal capillary degeneration, and is required for the development of diabetic retinopathy." (PMID 38474393, 2024). "Studies in mouse models of diabetic retinopathy revealed that the expression of CD40 limited to non-hematopoietic cells is sufficient to promote this disorder." (PMID 38474393, 2024). "AGE-mediated CD40 upregulation was functionally relevant since it enhanced CD40-driven expression of ICAM-1 and production of CCL2, events central to the pathogenesis of inflammatory disorders, including diabetic retinopathy." (PMID 38474393, 2024).
diabetic retinopathy (continued). "The molecular event downstream of CD40 that activates the PLCγ1–ATP–P2X7–proinflammatory cytokine cascade and promotes development of diabetic retinopathy is unknown." (PMID 35920844, 2022). "The events downstream of CD40 that trigger the PLCγ1–ATP–P2X7–proinflammatory cytokine cascade and promotes diabetic retinopathy are unknown." (PMID 35920844, 2022). "CD40 and TNF-α are also central to the development of diabetic retinopathy while CX3CL1 may play a role in the pathogenesis of this retinopathy." (PMID 26710229, 2015). "Similarly, CD40 is upregulated in retinal endothelial cells in mice with diabetic retinopathy and diabetic CD40-/- mice do not develop retinopathy." (PMID 26710229, 2015). "Importantly, diabetic Cd40−/− mice are protected from retinal upregulation of intercellular adhesion molecule 1 (ICAM-1), TNF-α, IL-1β, nitric oxide synthase 2 (NOS2) and C-C motif chemokine ligand 2 (CCL2) and do not develop diabetic retinopathy." (PMID 35920844, 2022).